MMP13 (matrix metallopeptidase 13)
Diseases named in the same sentence as MMP13 in open-access papers (continued):
Sharing a sentence is not in itself a finding about the gene and the disease.
colitis (15 papers, 2012 to 2025). Inflammation of the colon. "Moreover, Mmp13-/- animals were protected in experimental models of acute intestinal epithelial barrier dysfunction including cecal ligation and puncture and acute DSS colitis which was mechanistically linked to MMP13-induced, alternative shedding of membrane bound TNFα." (PMID 37207229, 2023). "On the basis of our histopathological analysis, we performed further characterization of Mmp13-/- mice compared to littermate controls by IF in colon tissue from chronic DSS colitis." (PMID 37207229, 2023). "The overexpression of inflammatory-related proteins, MMP-2, MMP-9 and MMP-13 has been reported to be involved in colon damage during colitis." (PMID 35159480, 2022). "Most MMPs, such as MMP-2, MMP-3, MMP-7, MMP-9, MMP-10, MMP-12, and MMP-13 are increased in colitis and CAC." (PMID 36776395, 2022). "Using the same mouse model, we further assessed the mRNA expression levels of Mmp3, Mmp10, and Mmp13 using quantitative real-time PCR (qPCR) of samples of mouse colitis tissue as well as CAC and normal colon tissues." (PMID 25742789, 2015). "As expected, we observed that MMP13−/− mice were less sensitive to DSS-induced colitis than MMP13+/+ mice and that this was correlated with reduced bioactive TNF levels." (PMID 23723167, 2013). "Libert and coworkers additionally found MMP7 to be up-regulated in DSS-induced colitis in MMP13 knockout mice." (PMID 23757215, 2013). "Measurement of colon length in MMP13+/+ and MMP13−/− mice 6 days after the start of DSS treatment revealed that MMP13 deficiency reduces the effect of DSS-induced colitis on the length of the colon." (PMID 23723167, 2013). "Thus, more studies are needed to fully comprehend DCLK1 isoform-specific regulation of MMP13-driven inflammation and colitis." (PMID 40839695, 2025). "Additionally, we used IMC to check for the levels of MMP13 in tissue sections of our DCLK1ΔIEC model of CR-induced colitis." (PMID 40839695, 2025). "Presumably, Mmp13 plays a minor role in ECM remodeling in colitis, whereas CAC was associated with significant up-regulation of its expression, which makes Mmp13 a promising gene candidate for the predicting of colitis-associated tumorigenesis; this requires further detailed study." (PMID 36901742, 2023). "In a transcriptomics study, the genes encoding MMP-7 and MMP-13 were overexpressed in CAC but not in colitis." (PMID 38288108, 2023). "Finally, the expression of the revealed hub genes related to acute colitis (C3, Tyrobp, Mmp3, Mmp9, Timp1) and CAC (Timp1, Adam8, Mmp7, Mmp13) was validated by qRT-PCR in the colon tissue of mice with acute colitis and colitis-driven adenomas." (PMID 36901742, 2023). "Additionally, moderate protection to dextran sulfate sodium (DSS)-induced colitis was observed in MMP13−/− mice compared to MMP13+/+ mice." (PMID 33802197, 2021). "Moreover, the levels of Mmp3, Mmp10, and Mmp13 proteins were also upregulated as determined with immunohistochemistry and western blotting of mouse colitis tissues and CAC tissues compared with normal colon tissues." (PMID 25742789, 2015). "The authors conclude that MMP13 is a potential therapeutic target for the treatment of colitis." (PMID 23757215, 2013). "In conclusion, LPS-induced shock and DSS-induced colitis induce MMP13 up-regulation in the gut." (PMID 23723167, 2013). "We confirmed the DCLK1-S/MMP13 axis in a knock- in mouse model overexpressing DCLK1-S, in conjunction with dextran sulfate sodium (DSS)- induced colitis." (PMID 40839695, 2025). "DCLK1 minimally colocalized with MMP13 in the untreated controls, but this colocalization became more prominent following DSS-induced colitis." (PMID 40839695, 2025). "Mmp13-/- mice and littermate controls underwent chronic DSS colitis which included 3 cycles consisting of DSS in drinking water for 7 days followed by tap water for 14 days per cycle." (PMID 37207229, 2023).
colitis (continued). "In fact, we noticed a decrease of MMP13 transcripts in chronic DSS colitis upon blockade of IL36R signaling, whereas injection of IL36R ligands into otherwise unchallenged wildtype mice resulted in elevated MMP13 levels in colon tissue." (PMID 37207229, 2023). "Upregulation of several secreted MMPs has been reported in the colonic mucosa of dogs with colitis, including MMP-1, MMP-3, and MMP-13, as well as MMP-2 and MMP-9." (PMID 35751094, 2022). "Our array data showed that metalloproteases and chemokines such as MMP10, MMP13, the CCs and CXCs are involved in the pathogenesis of DSS colitis." (PMID 22509329, 2012). "Despite the extensive studies of MMPs as candidate marker genes of colitis and CAC, to the best of our knowledge, the complex evaluation of the expression of Mmp3, Mmp7, Mmp9, and Mmp13 in acutely inflamed, adenomatous, and adjacent colon tissues has not yet been reported." (PMID 36901742, 2023). "In this study, we investigated whether MMP13 plays a role in epithelial barrier disruption during pathological events such as sepsis and IBD, by using endotoxemia and DSS-induced colitis models, respectively." (PMID 23723167, 2013). "During subcellular distribution, we discovered that both DCLK1-S and MMP13 were detected in the cytoskeletal fractions thereby implying that DCLK1-S-MMP13 axes is likely to expose the cryptic domains within ECM molecules to trigger both neutrophil infiltration and EMT as a prelude to colitis." (PMID 40839695, 2025). "Additional studies using in vivo models of colitis and CAC found that the expression signature of colitis (i.e., Mmp3 and Mmp9) versus that of CAC (i.e., Mmp7 and Mmp13) could predict the development of CAC in mice with dextran sulfate sodium (DSS)-induced colitis." (PMID 38288108, 2023). "On the basis of our findings, we hypothesized that the absence of MMP13 could be protective in this colitis model." (PMID 23723167, 2013).
fibrosis (15 papers, 2014 to 2025). the formation of excess fibrous connective tissue in an organ or tissue in a reparative or reactive process. "However, genes associated with cartilage fibrosis (such as Sparc and Col1a1) and hypertrophy (e.g., Ibsp, Bmp2, Mmp13, and Matn4) presented the highest expression levels at 6 weeks." (PMID 40722047, 2025). "The limited collagen found presently was similar to the amount caused by the administration of carvedilol in a model of fibrosis caused by the ligation of the bile duct, where the elevated expression of MMP-13 was accompanied by a reduced level of accumulated collagen." (PMID 30643808, 2018). "It was also reported that both AG and L-NAME upregulated MMP-13 mRNA expression in rat thioacetamide-induced fibrosis model." (PMID 26692194, 2015). "The interstitial collagenases MMP-2 and MMP-13 are upregulated during resolution of fibrosis, while TIMP-1 and TIMP-2 inhibit MMP activity." (PMID 26374068, 2015). "The dysregulation and effect of CTD-2528L19.6 in IPF is similar to the MMP13, whose expression is up-regulated during two stages after fibrosis whereas knockdown of MMP13 could aggravate the progression of lung fibrosis." (PMID 34112765, 2021). "In LX2 fibrosis cells, expression of genes involved in ECM accumulation (TIMP1) and degradation (MMP9, MMP12, MMP13) were notably altered via JT003 exposure." (PMID 33199780, 2020). "In some fibrosis models, MMP-2, MMP-9, and MMP-13 have a lower expression and concentration following treatment with MSCs." (PMID 25132856, 2014). "After MSC transplantation, the increased expression of MMP-2, MMP-9, MMP-13, and MMP-14 has been observed in several fibrosis models." (PMID 25132856, 2014). "As a result of this, ISO-injured mice presented with a significant reduction in LV MMP-13/TIMP-1 (by ~ 60%), MMP-9/TIMP-1 (by ~ 55%) and MMP-2/TIMP-2 (by ~ 65%) ratios at day 14 post-injury, in line with the increased LV fibrosis in these mice." (PMID 41382190, 2025). "In fibrosis mice, consistently, the expression of genes related to ECM accumulation (TIMP1, MMP3 and MMP8) were decreased and genes involved in ECM elimination (MMP2, MMP9 and MMP13) were notably upregulated after JT003 treatment." (PMID 33199780, 2020).
ovarian carcinoma (15 papers, 2016 to 2025). A malignant neoplasm originating from the surface ovarian epithelium. "The MMP12 82A/G polymorphism has been associated with increased susceptibility to ovarian cancer, and MMP13 in ascitic fluids of ovarian cancer patients has been identified as a potential marker for disease risk and survival outcomes." (PMID 40558552, 2025). "MMP-1 and MMP-13 have shown preliminary potential in the biochemical diagnosis of ovarian carcinoma—as diagnostic markers (in stand-alone or combined assays) and as auxiliary differentiation markers assayed together with the ROMA." (PMID 39682156, 2024). "In conclusion, collagenases MMP-1 and MMP-13 show bidirectional potential in the biochemical diagnosis of ovarian cancer." (PMID 39682156, 2024). "CAFs can also secrete TGF-β, which activates paracrine signaling, promoting the progression of OC due to the expression of various genes, including MMP11 and MMP13, promoting the metastasis of ovarian cancer cells to adjacent or distant sites." (PMID 37168385, 2023). "Secretion of MMP-13, known to stimulate ovarian cancer metastasis, was suppressed by 31%, 36%, and 34% following treatments with EGCG, I3C, and Pano." (PMID 37509102, 2023). "The deletion of miR-140 in ovarian cancers leads to the belief that it is related to invasion, involving matrix metalloproteinase-13 (MMP-13), fibroblast growth factor 2, and angiogenic VEGF-A." (PMID 34721577, 2021). "Our study also demonstrated that WISP2 deletion decreased Snail and MMP-13 levels in ovarian cancer cells." (PMID 32711570, 2020). "Overexpression of MMP13, along with CGA, EPHA3, PSMD9, PITX2, and PHLPP1, has been associated with poor response to platinum-based chemotherapy in patients with high-grade serous ovarian cancer (HGSOC), the most aggressive form of ovarian cancer." (PMID 37168385, 2023). "Furthermore, HIF-1a induced MMP13 expression appears to promote invasion and metastasis in ovarian cancer as well." (PMID 35311102, 2022). "Nonetheless, based on our current data, we hypothesize that the efficacy of MALAT-1 in promoting ovarian cancer progression could be mediated by up-regulation of MMP13 and down-regulation of MMP19 and ADAMTS1." (PMID 27227769, 2016). "Most of the tested metalloproteinases upregulated mRNA expression in both FIGO I/II and FIGO III/IV stages of ovarian cancer (MMP1, MMP13, MMP2, MMP9, MMP10, MMP7, MMP12 and MMP14) indicating profound modifications of the extracellular matrix." (PMID 38397798, 2024). "Progression-free survival depended on the expression level of MMP12, MMP13, PYCR1 and GPx1 in patients with ovarian cancer." (PMID 38397798, 2024). "In ovarian cancer, VEGF induces ETS1 expression by activating the PI3K/Akt and p38MAPK signaling pathways, which further activates MMP9 and MMP13 and promotes SKOV3 invasion and metastasis." (PMID 34659572, 2021). "Suppression of MALAT-1 resulted in downregulating the expression of MMP13 and up-regulating the expression of MMP19 and ADAMTS1 genes, indicating that MALAT-1 may involved in ovarian cancer by regulating the expression of the MMP13, MMP19, and ADAMTS1 genes." (PMID 27227769, 2016). "Thus, our data suggests that overexpression of MALAT-1 might promote ovarian cancer progression by regulating the expression of MMP19, ADAMTS1 and MMP13 genes." (PMID 27227769, 2016).
glioma (14 papers, 2014 to 2025). A benign or malignant brain and spinal cord tumor that arises from glial cells (astrocytes, oligodendrocytes, ependymal cells). "Importantly, clinical studies have also revealed that over-expression of MMP-13 is associated with tumor progression in glioma, and the highly invasive potential of cancer stem cells depends on MMP-13 enzymatic activity." (PMID 24599080, 2014). "miR-4262 expression downregulation inhibits glioma proliferation and migration by suppressing the expression of MMP2 and MMP13, and miR-34a inhibits glioma cell migration by regulating MMP-9." (PMID 36479040, 2022). "Previously, leptin was reported to be able to increase the expression of MMP-2, MMP-7 or MMP-9 in different cancer cells, as well as the expression of MMP-13 in glioma cells." (PMID 25948792, 2015). "Previous studies and clinical reports therefore suggest that MMP-13 can be used as a biomarker for glioma progression." (PMID 24599080, 2014). "We previously reported that MMP-13 expression is involved in cell migration and invasion astrocytes, oral squamous cell carcinoma, and glioma." (PMID 24599080, 2014). "Results from this study reveal that osthole inhibits MMP-13 expression in normal human glioma cells, in addition to those selected for migration-prone characteristics." (PMID 24599080, 2014). "A recent clinical study reported increased MMP-13 expression in glioma specimens compared with that of normal brain tissues." (PMID 24599080, 2014). "Our results showed that osthole inhibits FAK phosphorylation and MMP-13 expression in human glioma cells." (PMID 24599080, 2014). "We also tested whether major proteases are also affected by hrGDF15 treatment, and thus we examined the expression of Matrix metalloproteinase 13 (MMP13), a metalloproteinase with a crucial role in glioma cell invasion as well as in other cancer types." (PMID 31412547, 2019). "Also, we found that PINCH1, RhoA and MMP13 play a crucial role being regulated by the RSU-1/GDF15 interplay leading to affection of the final invasive phenotype of glioma cells." (PMID 31412547, 2019). "In glioma cells, the up-regulation of MMP-13 by leptin was mediated through p38 MAP kinase and NF-κB pathway, while in pancreatic cancer cells, we found that the expression of MMP-13 was regulated through JAK2/STAT3 signaling pathway in response to leptin stimulation." (PMID 25948792, 2015). "Importantly, osthole also inhibits FAK phosphorylation and MMP-13 expression in migration-prone glioma cells." (PMID 24599080, 2014). "Moreover, high expression of MMP-13 was detected more often in advanced grades of glioma." (PMID 24599080, 2014). "RSU-1 is significantly upregulated in more aggressive glioma cell types, and silencing RSU-1 can reduce STAT6 and MMP13 to inhibit invasion." (PMID 39458959, 2024). "In glioma grade IV, highly activated DEGs included STOM, IGHG4, CXCL13, MMP13, and CAPN6, while highly downregulated DEGs included JAZF1-AS1 and ELDR." (PMID 33948562, 2021). "The inhibition of migration activity by osthole likely involves down-regulation of MMP-13 and cell motility-dependent FAK in human glioma cells." (PMID 24599080, 2014). "Our study confirms previous reports that osthole induces cell death in human glioma cells, and indicates that osthole effectively inhibits FAK activation, MMP-13 expression, and cell migration." (PMID 24599080, 2014). "We have shown that osthole effectively induces cell death in human glioma cells, and also that this agent significantly reduces FAK phosphorylation and MMP-13 expression in human glioma cells." (PMID 24599080, 2014). "We observed the down-regulation of MMP-13 and cell motility dependent FAK in P10 migration-prone human glioma cells treated with osthole." (PMID 24599080, 2014). "Still only BMP2, MMP13, MMP2, LCK, MMP9, and AR have been reported to affect the glioma invasion." (PMID 39458959, 2024).
glioma (continued). "Similarly, leptin enhances the production of matrix metalloproteinase (MMP)-13 through the p38-mitogen activated protein (MAP) kinase and nuclear factor (NF)-κB pathway, thus promoting the migration and invasion of C6 glioma cells." (PMID 36105407, 2022).
knee osteoarthritis (14 papers, 2014 to 2025). "Col2 and Aggrecan expression level was a representative marker of cartilage anabolic activity, and MMP13 was an important catabolic marker of knee osteoarthritis progression." (PMID 38742846, 2024). "Induction of knee osteoarthritis caused a loss in muscle coordination, knee swelling, elevations in the inflammatory mediators (TNF-α & TGF-β1), and the oxidative stress markers (MMP-13 & NOX-4) in joint tissues." (PMID 37878123, 2023). "We found that when guinea pig spontaneous knee osteoarthritis occurs,the superficial chondrocytes in the tibial plateau degenerate first, and the chondrocytes undergo hypertrophic changes, which lead to the synthesis and secretion of MMP-13 proteins." (PMID 33910538, 2021). "Western blots were evaluated for differences in MMP-13, TIMP-1, NF-κB, IκB-β, and COL2A1 protein expression among the groups of rats with MIA-induced knee osteoarthritis." (PMID 28594958, 2017).